HIF1A (hypoxia inducible factor 1 subunit alpha)
Diseases named in the same sentence as HIF1A in open-access papers (continued):
Sharing a sentence is not in itself a finding about the gene and the disease.
breast cancer (continued). "MiR-20b was also reported to involve regulation of VEGF expression by targeting HIF-1α and STAT3 in MCF-7 breast cancer cells." (PMID 25364498, 2014). "It is consistent with previous reports of overexpression of HIF-1α and CAIX correlating with a poor prognosis in several types of cancer, including NPC, laryngeal carcinoma, breast cancer and non-small cell lung cancer." (PMID 25377659, 2014). "It has been reported that hypoxia-induced expression of HIF-1α leads to the release of LOX, an enzyme that crosslinks extracellular matrix proteins such as collagen and promotes breast cancer metastasis." (PMID 25238333, 2014). "The result indicated that murine tumor cell lines (Murine K1735 melanoma, murine melanoma B16F10, murine breast cancer 4T1, and murine CT26 colon cancer) express Cx43 and HIF-1α." (PMID 25548899, 2014). "We have performed a comprehensive study, by integrating microRNA expression, gene expression and HIF-1α and HIF-2α chromatin immunoprecipitation (ChIP) data from the same breast cancer cell line MCF-7." (PMID 24517586, 2014). "One such study showed ARRB1 to co-localise and physically interact with hypoxia-inducible factor 1A (HIF1A) in the nucleus of breast cancer cells to potentiate HIF1-dependent transcription, thereby mediating metastatic growth of breast cancer cells." (PMID 24837709, 2014). "Our previous results show that HIF-1α stabilization was accompanied by an increase of membrane P-cadherin expression, which was co-expressed with GLUT1 and CAIX in breast cancer cells." (PMID 25269858, 2014). "Clinical studies have shown that both HIF-1α and LOX are overexpressed in breast cancer patients, and this overexpression increases with disease progression, resulting in a high mortality rate." (PMID 25238333, 2014). "Accordingly, we demonstrated that the inhibition of CDH3, HIF-1α, GLUT1 and CAIX in basal-like breast cancer cells significantly reduces their MFE, an important measure of breast cancer stem cell activity." (PMID 25269858, 2014). "Immunohistochemical analysis of a xenograft and a human breast cancer tissue array revealed a significant correlation between NMB-R and HIF-1α expression." (PMID 24349381, 2013). "In this study, we retrospectively evaluated for the first time the role of angiogenic markers such as VEGF, HIF-1α and MVD, in BRCA1-2 carrier and BRCAX breast cancers." (PMID 23326384, 2013). "It is known that there is an interaction between HIF-1α and BRCA1 carrier cancers, but little has been reported about angiogenesis in BRCA1-2 carrier and BRCAX breast cancers." (PMID 23326384, 2013). "In particular, our results demonstrate that a low oxygen tension stimulates through the ERK1/2 transduction pathway the HIF-1α dependent expression of GPER, which contributes to the regulation of VEGF in both CAFs and breast cancer cells." (PMID 23947803, 2013). "In this study, we investigated the expression of VEGF and HIF-1α and microvessel density (MVD) in 26 BRCA1-2 carriers and 58 BRCAX compared to 77 sporadic breast cancers, by immunohistochemistry." (PMID 23326384, 2013). "Immunohistochemical staining for ER, PR, HER-2, Ki-67, HIF-1α, SDHA, and SDHB was performed on tissue microarrays of 721 breast cancers." (PMID 23888270, 2013). "Therefore, we hypothesizes that EGCG directly targets both of tumor cells and tumor vasculature, thereby inhibiting tumor growth, proliferation, migration, and angiogenesis of breast cancer, which is mediated by the inhibition of HIF-1α and NFκB activation as well as VEGF expression." (PMID 23638734, 2013). "In accordance to our results, it has also been demonstrated that HIF-1α enhances tumor-initiating cell frequency in vivo in part by regulation of the expression of CD133 and the Notch pathway in breast cancer cells." (PMID 23840432, 2013).
breast cancer (continued). "Since previous study demonstrated that there was little expression of phosphor-Akt in breast cancer cell lines MCF-7 and MDA-MB-231, we therefore focused on the HIF-1α proteaosme degradation pathway." (PMID 23457597, 2013). "Interactions of HIF-1α with the Notch intracellular domain enhances the regulation of Notch transcriptional targets, such as the HEY genes, and promotes EMT in breast cancer." (PMID 22225988, 2012). "JMJD2C (KDM4C) is induced by HIF-1α to mediate epigenetic regulation of HIF-1α downstream genes involved in metabolic reprogramming and lung metastasis of breast cancer." (PMID 23241400, 2012). "In agreement with our observations, a HIF-1α-dependent effect on tumor growth was demonstrated recently in both MDA-MB-231 and MDA-MB-435 breast cancer xenografts." (PMID 22225988, 2012). "HIF1α ChIP-chip binding locations have been reported in cell lines of diverse tissue origin, namely HepG2 hepatocarcinoma cells, MCF-7 breast cancer cells and U87 glioma cells, showing differences in the binding sites identified in each experiment." (PMID 23029193, 2012). "HIF-1α regulates expression of several members of the Notch pathway, CD133 and markers of the basal lineage in mammary tumors." (PMID 22225988, 2012). "We determined that the basal breast cancer cell lines (BT20, MDA-MB231, MDA-MB157) had consistently higher mRNA levels of both HIF1A (HIF-1α) and EPAS1 (HIF-2α) when compared to the luminal cell lines (MCF7, BT474, CAMA1)." (PMID 21672245, 2011). "Leptin uses several signaling pathways, including the activation of HIF-1α and NF-κB, for the upregulation of VEGF in breast cancer cells under normoxic conditions." (PMID 21731759, 2011). "Since we have recently shown that 62% and 76% of breast cancer patients express VEGF and HIF-1α, respectively, in their CTCs, it was of interest to identify the potential expression of this transcription factor in CTCs." (PMID 21663619, 2011). "Our study showed that both HIF-1α and HIF-2α accumulated in breast cancer cells with hypoxia and they potentiated Notch signaling." (PMID 20010940, 2010). "SK-BR-3 cells have a higher basal level expression of both HIF-1α and HIF-2α compared with other breast cancer cells." (PMID 20010940, 2010). "Hypoxia and Hif-1a have been shown to upregulate CXCR4 in carcinomas such as lung cancer, oral squamous cell carcinoma, breast carcinoma, and renal cell carcinoma." (PMID 20102637, 2010). "DCQ was found to decrease the expression levels of the hypoxia inducible factor (HIF-1α) mRNA and protein in the human colon carcinoma cell line T-84, and in EMT6 mouse mammary carcinoma cells and Lewis Lung Carcinoma (LLC) cells." (PMID 21078189, 2010). "We have examined the role of the key pathway members regulating HIF-mediated transcription, including HIF-1α, the PHDs, FIH and CAIX in a series of breast cancers classified into intrinsic subtypes." (PMID 19165203, 2009). "HIF-1α-positive CTCs co-exist with VEGF- or VEGFR2-positive CTCs in 16 (47%) and 14 (41%) breast cancer patients, respectively." (PMID 19919679, 2009). "In this study, we confirmed that HIF-1α is highly expressed in NSCLC tissue, as was found in breast cancer." (PMID 19245702, 2009). "We have therefore examined the role of the key pathway members regulating HIF-mediated transcription including HIF-1α, PHD1, PHD2, PHD3, VEGF and FIH in a series of familial breast cancers stratified by BRCA status and intrinsic phenotypes." (PMID 19724277, 2009). "The preceding studies provide proof of principle that the HIF-1α and TGF-β signaling pathways in breast cancer cells promote skeletal metastases." (PMID 19727403, 2009). "Systemic inhibition of HIF-1α by 2ME2 significantly decreased osteolytic lesion area and reduced tumor burden in a prevention model of MDA-MB-231 breast cancer bone metastasis, consistent with the previous studies using 4T1 cells." (PMID 19727403, 2009).
breast cancer (continued). "Immunoperoxidase staining for HIF-1α, PHD1, PHD2, PHD3, VEGF and FIH was carried out in 125 (38 BRCA1, 33 BRCA2 and 54 BRCAX) breast carcinomas." (PMID 19724277, 2009). "In this study, we demonstrate that intracellular overexpression or extracellular administration of MIF increased HIF-1α protein expression and HIF-1-dependent gene expressions in MCF-7 breast cancer cells." (PMID 18493321, 2008). "Tissue sections of the primary tumour and a lymph node metastasis of 60 patients with breast cancer were immunohistochemically stained for the hypoxia-markers carbonic anhydrase 9 (CA9), hypoxia-inducible factor-1α (Hif-1α) and DEC-1 and for CD34/Ki-67." (PMID 16251878, 2005). "By reducing HIF-1α protein accumulation, resveratrol may limit MMP and VEGF expression, thereby inhibiting tumor growth and angiogenesis, though direct evidence in breast cancer is still emerging." (PMID 41614951, 2026). "In vivo studies in other cancers have shown that curcumin can down-regulate HIF-1α; however, breast cancer has not yet been studied extensively in this context." (PMID 41614951, 2026). "By reducing reactive oxygen species (ROS), EGCG may inhibit HIF-1α protein accumulation, thereby facilitating HIF-1α protein degradation via the VHL-mediated ubiquitin-proteasome pathway, although direct evidence in breast cancer cells remains limited." (PMID 41614951, 2026). "In addition to HIF-1α, research has shown that HIF-2α, which is controlled by upstream regulator FOXA1, plays a distinct function in the development and angiogenesis of breast cancer." (PMID 41614928, 2026). "Our findings highlight the therapeutic potential of targeting HIF-1α-controlled DSG2-mediated desmosome junction conversion and position hirudin as a promising CTC clusters dissociator optimized for the clinical prevention of breast cancer metastasis." (PMID 41381723, 2025). "Thus, it is possible that ADAM12 is induced by HIF-1α in SIP, as in breast cancer, and that this induces the EGFR activation pathway." (PMID 41346909, 2025). "HIF-1α and HIF-2α play distinct roles in breast cancer biology, and therapies targeting both isoforms may have different effects depending on the tumor subtype." (PMID 40901111, 2025). "Additionally, Molidustat (10–50 μM) has been demonstrated to stabilize HIF-1α and induce the expression of VEGF in MDA-MB-231 breast cancer cells." (PMID 40710374, 2025). "Moreover, HIF-1α stabilization enhances VEGF-A expression, and the binding of VEGF-A/VEGFR-1 promotes VM formation in aggressive and highly invasive breast cancer cells." (PMID 41400702, 2025). "Furthermore, in human breast cancer samples, WWOX expression was inversely correlated with the level of the glucose transporter GLUT1, a direct target of HIF1α." (PMID 41007296, 2025). "We observed a similar dichotomy in HER2-positive breast cancers, where a favourable WWOX/HIF1A ratio facilitates robust DNA repair and counteracts hypoxia-induced signalling, which would otherwise promote angiogenesis and glycolytic reprogramming linked to poor prognosis." (PMID 41007296, 2025). "Our findings suggest that IVIM may be usefully combined with DKI to help predict the expression levels of Ki-67, HIF-1α, and VEGF in breast cancer, generating hypotheses for future research." (PMID 41189947, 2025). "In basal-like and HER2-positive breast cancers, we demonstrated that a low WWOX/HIF1A ratio is particularly detrimental, as it triggers HIF1α-mediated upregulation of immunosuppressive mediators such as TLR4, NOTCH1, PTX3, and IL6R, alongside glycolytic enzymes like GLUT1 and HK2." (PMID 41007296, 2025). "For luminal breast cancers, we found that high WWOX/HIF1A ratios demonstrate a more robust anti-tumour immune response, as evidenced by increased expression of CD8A and FOXP3, which are instrumental in recruiting cytotoxic T-cells and suppressing pro-tumourigenic inflammation." (PMID 41007296, 2025).
breast cancer (continued). "Single-cell sequencing analyses uncovered a link between the infiltration of NK cells and absence of hypoxia-inducible factor 1-alpha (HIF-1α) expression in murine breast cancer tumors." (PMID 40303301, 2025). "Our study demonstrates that DATS disrupts glycolytic metabolism in breast cancer cells, as evidenced by a significant reduction in glucose uptake, downregulation of key glycolytic regulators (GLUT1, LDHA, and HIF1α), and diminished lactate production following combination treatment with DOX." (PMID 40861817, 2025). "Notably, PDK3 expression is elevated in breast cancer tissues, akin to PDK1, and is induced by HIF-1α, exhibiting increased expression levels." (PMID 41465397, 2025). "For example, SUMOylation‐dependent HIF‐1α/CLDN6 negative feedback contributes to the metastasis of breast cancer." (PMID 40954549, 2025). "Furthermore, PDK1 is a direct transcriptional target of hypoxia-inducible factor 1-alpha (HIF-1α), establishing a mechanistic link between hypoxic conditions and glycolytic reprogramming in breast cancer." (PMID 41465397, 2025). "O-GlcNAcylation of HIF-1α promotes GLUT1 transcription, whereas suppression of O-GlcNAcylation leads to the hydroxylation of HIF-1α and its subsequent proteasomal degradation in human basal-like breast cancers." (PMID 39178944, 2024). "Downregulation of HIF-1α by miR-622, which deactivates genes within the EMT pathway, culminates in decreased levels of Snail, Slug, and vimentin proteins through miR-30a, consequently attenuating the invasion and migration capacities of breast cancer cells." (PMID 38339408, 2024). "Excess HIF-1α-induced VEGF stimulates local vessel growth and can even enter the systemic blood circulation where it is critical for establishing vasculature within the developing breast cancer." (PMID 39439572, 2024). "In breast cancer MCF7 cells and murine mammary 4T1 cells, 2DG inhibition of glycolysis occurs through ROS inhibition and a cell signaling feedback loop (2DG/ROS/PI3K/AKT/HIF1α/HK2/glycolysis)." (PMID 39251846, 2024). "Survivin, a downstream signaling molecule of HIF-1α, is a strong inhibitor of apoptosis, which can be regulated positively by HIF-1α and expressed in common malignant tumors, such as breast cancer, BCa, renal cancer, colorectal cancer, neuroblastoma, and ovarian cancer, but not in normal tissues." (PMID 39309474, 2024). "Targeting HIF1A could potentially inhibit the metastatic spread and improve the overall survival of patients with OSCC and breast cancer." (PMID 39458948, 2024). "Hypoxia-inducible factor 1α (HIF-1α) is a driver of tumor cell metastasis through epithelial–mesenchymal transition (EMT) in solid tumors, while autophagy increases invasiveness and drug resistance in the hypoxic environment of breast cancer." (PMID 38339408, 2024). "Therefore, our findings propose isonahocol D2 as a potential therapeutic agent targeting HIF1A conditions of OSCC and breast cancer." (PMID 39458948, 2024). "In the context of breast cancer cells, the activation of Peroxisome Proliferator-Activated Receptor γ (PPARγ) triggers an upregulation of HIF1α expression, and HIF1α, in turn, mediates PPARγ-induced activation of autophagy, thereby promoting the survival of MDA-MB-231 breast cancer cells." (PMID 38315272, 2024). "We used a real-time transcriptional activity assay known as TRACER (TRanscriptional Activity CELL aRray) to measure the dynamic activity of six transcription factors involved in EMT signaling specific for breast cancer (TWIST1, SNAIL, HIF1a, RUNX1, RUNX2, and NOTCH1)." (PMID 38398186, 2024). "Expression of hypoxia markers HIF-1α and carbonic anhydrase IX (CAIX) have significant prognostic implications in ERα positive breast cancer, where their increased abundance correlates with decreased disease-free survival in patients with luminal A or luminal B disease." (PMID 39282472, 2024).
breast cancer (continued). "Moreover, under hypoxic conditions, OPN modulates HIF1α-induced VEGF expression via the ILK/NF-κB signaling cascade, which ultimately culminates in breast cancer progression and angiogenesis." (PMID 39062100, 2024). "In addition, SND1, a known pro-oncogenic protein, augments the binding of HIF-1α to EZH2, contributing to the development of breast cancer induced by the polyomavirus middle T antigen (PyMT)." (PMID 38911968, 2024). "So, it is suggested that the restriction in HIF1α and MMP activities may have therapeutic prospects against breast cancer." (PMID 39132498, 2024). "In breast cancer MCF7 cells, miR20b targets HIF-1α to suppress its expression." (PMID 38766303, 2024). "Also, HIF-1α collection levels were significantly decreased in MDA-MB-231 and MCF-7 breast cancer cell lines." (PMID 38970040, 2024). "The miRNA-triggered entropy-driven reconfiguration of the spatiallylocalized circuit leads to the programmable, cooperative bis-gene-silencingof HIF-1α and EGR-1 mRNAs, resulting in the effective and selectiveapoptosis of breast cancer cells and effective inhibition of tumorsin tumor bearing mice." (PMID 39012486, 2024). "Similarly, in breast cancer, particularly in triple-negative breast cancer (TNBC), HIF1A drives metastasis by regulating genes that promote epithelial-mesenchymal transition (EMT) and stemness." (PMID 39458948, 2024). "Under hypoxic conditions, hypoxia-inducible factor 1 α (HIF-1α) can synergize with chemokine signals from mesenchymal stem cells to trigger colony-stimulating factor 1 (CSF-1) and chemokine receptor type 5 (CCR5) gene transcription in breast cancer cells." (PMID 39192979, 2024). "Given that the expression of HIF-1α is high in ER+ breast cancer, we speculated that ERα transcriptionally activates UBE2M through HIF-1α." (PMID 39138151, 2024). "In addition to regulating HIF-1α and HIF-2α, we find that HIF-1β is also decreased under hypoxic conditions in the breast cancer cell lines we assessed." (PMID 36831670, 2023). "In OC-treated breast cancer cells, HIF1α mRNA and protein are regulated by PI3K/AKT signaling, not in response to oxygen conditions." (PMID 37957150, 2023). "Notably, liver-metastatic breast cancer cells have high HIF-1α activity, which induces PDK1 expression and glycolysis, and knockdown of HIF-1α or PDK1 inhibits breast cancer liver metastasis." (PMID 37444501, 2023). "In addition, its function in EMT was described based on crosstalk between HIF-1α and estrogen with NOTCH signaling in breast cancer." (PMID 36982170, 2023). "VEGF is stimulated by HIF-1α and NFκB and leptin, through the activation of HIF-1α and NF-kB via canonic (MAPK, PI-3K) and non-canonical (JNK, p38 MAP, PKC) signaling pathways, upregulates VEGF in breast cancer." (PMID 37686525, 2023). "Whilst the potential clinical utility of HIF-1α and CAIX in ER + breast cancer has been discussed by several authors, the relationships between the in vivo tumour pathophysiology and the expression of hypoxia-regulated proteins are underexplored for this cancer type." (PMID 37166494, 2023). "It was showed that gallic acid effectively against metastasis in various cancer cell types such as myeloid leukemia, breast cancer and ovarian cancer by modulating multiple signalling pathways, including Akt/mTOR, ERK, MMPs, NFκB, PTEN/Akt/HIF-1α/VEGF pathways." (PMID 37957642, 2023). "The current data also indicated that mTOR/HIF-1α is a dominant pathway for DPP-4 inhibition-induced autophagy in breast cancer cells, but not in normal breast epithelial cells." (PMID 37760498, 2023). "Mechanistically, TOPK was found to mediate hypoxia‐induced epithelial‐mesenchymal transition (EMT) and the invasion of NSCLC cells via the HIF‐1a/snail axis, and promote the EMT and invasion of breast cancer cells by upregulating TBX3 in TGF‐β1/Smad signalling." (PMID 37226642, 2023).